SNORA63D (small nucleolar RNA, H/ACA box 63D)
Gene: Small nucleolar RNA gene on chromosome 3 (183,451,857 to 183,451,988, forward strand). Ensembl gene ENSG00000201229.
Homologues: Orthologues: chimpanzee SNORA63 (100% identical), dog SNORA63 (87% identical), pig SNORA63 (85% identical), guinea pig SNORA63D (81% identical), tropical clawed frog SNORA63 (70% identical), tropical clawed frog SNORA63 (68% identical), zebrafish SNORA63 (66% identical). Paralogues in human: SNORA63E (75% identical), SNORA63 (74% identical), SNORA63C (72% identical), SNORA63 (71% identical), SNORA63B (66% identical), SNORA63 (65% identical), SNORA63 (64% identical), SNORA63 (61% identical), SNORA63 (39% identical).